CXCR4 (C-X-C motif chemokine receptor 4)
Diseases named in the same sentence as CXCR4 in open-access papers (continued):
Sharing a sentence is not in itself a finding about the gene and the disease.
tumor (continued). "Noteworthy, during dynamic migration, largely guided by the CXCR4/CCL12 axis, IFN-DCs were found to modify their motion in order to interact with drug-treated cancer cells and then to take up tumor Ags." (PMID 28439087, 2017). "It stimulates the tumor production of bone-active factors (PTHrP, IL-11, ET-1) and prometastatic factors (VEGF, CXCR4, CTGF, MMPs), which disrupt normal bone remodeling and promote invasion, angiogenesis, and homing of tumor cells to bone." (PMID 29156807, 2017). "It was reported in previous literature that in the tumor microenvironment, CXCL12 secreted by stromal cells or immune cells had an effect on CXCR4 expressed by ECSCs, mediating its invasion and metastasis." (PMID 28193907, 2017). "Targeting tumor-specific growth promoting pathways is important for successful cancer therapy, and the CXCL12/CXCR4 signaling axis is involved in tumor progression and migration in multiple tumor types." (PMID 28055968, 2017). "We demonstrated that M-E5 exhibited higher affinity for CXCR4-overexpressing MCF-7 and HepG2 tumor cells as compared to free E5, and efficiently inhibited the tumor cells migration." (PMID 28793338, 2017). "QRHX inhibited tumor cell-TAMs interactions via the suppression of cancer-related inflammation and probably blocking the response of macrophages to tumor signals, CXCL12/CXCR4/JAK2/STAT3 axis." (PMID 28630636, 2017). "Cancer patients derived Tregs usually express a distinct profile of chemokine receptors, such as CCR4, CXCR4 and CCR5, which facilitates their migration into tumors in response to the corresponding chemokine ligands derived from tumor microenvironment." (PMID 29100374, 2017). "In turn, MSC-like CAFs secreted CXCL12 that binding to CXCR4 on tumor cells induced an EMT, which ultimately promoted metastasis to secondary tumor sites." (PMID 29069870, 2017). "In the xenograft tumor model, SDF-1/CXCR4 axis not only promoted homing and colonization of cancer cells to a distant tissue, but also enhanced the growth of secondary tumor." (PMID 28938623, 2017). "In the local hypoxic areas of the tumor microenvironment HIF-1α triggers CXCL12 (SDF-1) expression which in turn increases migration, adhesion, and homing of CXCR4+ progenitors." (PMID 28197019, 2017). "We also evaluated the effect of Rhy on the expression of CXCR4, MMP-9, and MMP-2, proteins which play a critical role in tumor metastasis." (PMID 28534824, 2017). "Forward selected, proportional Cox regression of survival modifying parameters (T, N, R, G, tumor localization, MMP2/9, TIMP1/2, CXCR4, and CXCL12) identified CXCR4 being the only survival-modifying parameter in HNSCC." (PMID 29348861, 2017). "Our results revealed that CXCR4 was responded to HNRNRKP2 and represented an important downstream effector of HNRNPKP2 that potentially mediated the effects of this lncRNA on tumour metastasis." (PMID 28403883, 2017). "CXCL12, CXCR4, JAK2, and STAT3 can not only play significant role in tumor cell or macrophage, but also other cells, such as T lymphocyte, neutrophils, tumor-associated fibroblast, and endothelial cells." (PMID 28630636, 2017). "The combined inhibition of HER2 and CXCR4 by trastuzumab and AMD3100 led to further reduction for primary tumor growth." (PMID 28405006, 2017). "Staining for CXCR4 and ETA was predominantly detected on the plasma membrane of the positive tumor cells." (PMID 29163802, 2017). "Most recently, it was shown that macrophage migration inhibitory factor (MIF)/CXCR4 and monocyte chemoattractant protein-1 (MCP-1)/CCR2 pathways are responsible for migration of MSCs in the tumor microenvironment of the lungs." (PMID 28798777, 2017). "Univariate analysis indicated that tumor site, AJCC stage, recurrence, and metastasis were significant prognostic factors for DFS (all P < 0.05), whereas CXCR4 expression, recurrence, and metastasis were significant prognostic factors for OS (all P < 0.05)." (PMID 29020982, 2017).
tumor (continued). "We used a tumor cell implantation (TCI) model and observed that CXCR4, p-CaMKII and p-CREB were persistently up-regulated in spinal neurons." (PMID 28638088, 2017). "These samples are used to confirm immunohistochemistry analysis using reverse transcription quantitative polymerase chain reaction (RT-qPCR) as a second method to analyze CXCR4, SMAD4, SOX9 and IFIT3 mRNA expression of the tumor." (PMID 28356064, 2017). "CXCR4 and ACKR3 as well as CXCL12 are frequently overexpressed in human cancers where they contribute to tumor growth and metastasis formation." (PMID 29156704, 2017). "Synchronous with the changes in HIF/BNIP3/BCL-xL/VEGF/CXCR4 upon artificial miR-199a-5p overexpression, PC-3 and DU145 cells showed reduced growth, invasiveness and tumor angiogenic ability but increased apoptosis (as assessed by the TUNEL assay)." (PMID 29137361, 2017). "CXCR4/CXCL12 axis triggers PI3K-Akt and Ras-Erk signalling pathways, which mediates tumor cells survival and proliferation." (PMID 28793338, 2017). "In contrast to small molecule and peptide inhibitors of CXCR4, ulocuplumab, as well as another IgG4 CXCR4 antibody, LY26245587, and an IgG1 CXCR4 antibody hz515H7, can induce tumor cell death via a mechanism reminiscent of PCD, similarly to PF-06747143." (PMID 28526063, 2017). "Exposure of bivalent tumor cells to microenvironmental stress, such as growth factor deprivation, results in loss of bivalency and gene activation, thereby contributing to stress-dependent induction of CXCR4 and phenotypic transition of cells from CXCR4 negative to CXCR4 positive states." (PMID 27528222, 2016). "The ligand for CXCR4, namely, CXCL12, is secreted by ECs and the immune cells in tumor microenvironment, which highlights the importance of CXCL12/CXCR4 axis in the maintenance of GSCs in vascular niches." (PMID 26977157, 2016). "We further noticed that the proliferation marker Ki-67 and tumor-promoting factors (MMP9, CXCR4) were significantly downregulated by resveratrol in CRC cells." (PMID 26959057, 2016). "G protein coupled receptor kinase 3 (GRK3) is a negative regulator of CXCR4 activity, and we show that GRK expression correlates with tumorigenicity, molecular subtype, and metastatic potential in human tumor microarray analysis." (PMID 27049755, 2016). "There is evidence that disruption of CXCR4 results in a reduction of GSC markers and reduction in tumor cells proliferation." (PMID 27863376, 2016). "The CXCR4/CXCL12 axis represents a major mechanism in tumor growth and metastasis, and its role in the cancer cell-tumor microenvironment has recently been studied regarding cancer progression and the attraction/activation of leukocytes." (PMID 27528023, 2016). "Taking advantage of the conserved intercommunication between human tumor cells and the zebrafish host, we blocked TNBC early metastatic events by chemical and genetic inhibition of CXCR4 signaling." (PMID 26744352, 2016). "CD31-positive endothelial cells also expressed CXCR4 and A2BR stimulation increased CD31+ cells within tumor lesions." (PMID 27590504, 2016). "CXCR4 showed a nuclear positivity in all samples, but only CXCL12 expression in tumor endothelial cells was significantly correlated with shorter survival." (PMID 27018053, 2016). "In this context the important role of the CXCL12-CXCR4 axis is further supported by recent studies which show upregulated expression of CXCR4 and CXCL12 after chemotherapy, thus leading to invasive and metastatic tumor progression." (PMID 27835905, 2016). "CXCR4, a receptor for the stromal cell–derived factor-1 (CXCL12/SDF-1α), promotes tumor progression, angiogenesis and drug resistance." (PMID 31656694, 2016). "This antibody also inhibited CXCR4 and SDF-1 mediated cell signaling including activation of MAPK and AKT in tumor cells expressing CXCR4." (PMID 26954567, 2016). "We also investigated highly the immunochemical expression of CXCR4, MIF and Bcl-2 in HCT-116/OxR tumor sections." (PMID 27668882, 2016).
tumor (continued). "Concurrently, inhibiting c-Abl (and thus geminin function), RAGE or CXCR4 prevented MSCs recruitment to GemOE cells in vitro and in vivo, and decreased the TIC, basal and EMT phenotypes in these tumor cells." (PMID 26989079, 2016). "In this study, we show that a combined therapy of CXCR4 knock-down and radiation decreases the perivascular invasion of GBM and increases the sensitivity of tumor cells to radiation therapy." (PMID 27863376, 2016). "While the tumor accumulation of [68Ga]pentixafor is higher than activity uptake in all other organs, leading to excellent tumor/background ratios, uptake of [68Ga]NOTA-pentixafor in the Daudi xenografts is surprisingly low, albeit CXCR4 specific." (PMID 27655427, 2016). "The omental tumor tissues from SKCXCR2-bearing mice expressed higher mRNA levels of CCL20 in chemokines and CXCR4 in chemokine receptors compared to those from SKA-bearing mice." (PMID 27723802, 2016). "Emerging evidence indicates that chemokine receptors pathways control tumor development, including tumor growth, progression, and metastasis and that CXCL12/CXCR4 activation induces migration and metastatic processes." (PMID 26934559, 2016). "Recent evidence points to an even greater importance for CXCR4 expression in TNBC, which contributes to tumor size and metastatic potential as well as predicts poor prognosis in terms of overall and disease-free survival." (PMID 27049755, 2016). "HIF-1 consequently induces tumor secretion of CXCL12, which binds to CXCR4 on proangiogenic bone marrow–derived cells (BMDCs), recruiting them to become endothelial cells within the tumor." (PMID 27863376, 2016). "Functionally, we found that CXCR4 blockade using a CXCR4-specific inhibitor, AMD3100, significantly blocked B cell-mediated killing of 4T1 tumor." (PMID 27528023, 2016). "Data showing the effect of AMD3100 on tumor cells migration towards MBVE and HBMVE suggest that CXCR4 plays an important role in GBM cell migration through the perivascular niche." (PMID 27863376, 2016). "In this present study, we examined new mechanisms contributing to direct B cell-mediated antitumor immunity, including the impact of IL-2, the CXCR4/CXCL12 pathway and perforin in mediating tumor regression after the adoptive transfer of B effector cells." (PMID 27528023, 2016). "CXCR4-PET was positive in 8/10 patients and revealed more lesions with significantly higher tumor-to-background ratios than SSTR-PET." (PMID 26843617, 2016). "Blockade of CXCR4 using a CXCR4-specific inhibitor, AMD3100, significantly reduced the killing of 4T1 tumor cells by 4T1 TDLN B cells." (PMID 27528023, 2016). "Another process by which the CXCR4/CXCL12 axis contributes to GBM growth is its ability to recruit endothelial and marrow cells to support tumor vasculogenesis and angiogenesis." (PMID 26977157, 2016). "CXCL12 and its receptor CXCR4 were shown to be important for recruitment of immunosuppressive cells such as MDSC and Tregs in the tumor microenvironment and for tumor angiogenesis." (PMID 27590504, 2016). "Further, we revealed that the increased expression of EphA1 in HCC cells led to an increased SDF-1 concentration in the tumor microenvironment, which in turn activated the SDF-1/CXCR4 axis and enhanced the recruitment of EPCs to HCC." (PMID 27066828, 2016). "Blocking the CXCR4/CXCL12 axis with low molecular weight (LMW) agents, peptides or antibodies has been shown to reduce tumor growth, metastasis and to sensitize cytotoxic chemotherapy in preclinical models." (PMID 26848769, 2016). "CXCR4 antagonists, such as Plerixafor (AMD3100) and T14003 analogs, can damage adhesive tumor-stroma interactions and therefore render cancer stem cells vulnerable to the cytotoxic drugs." (PMID 31656694, 2016). "The stromal cell-derived factor-1 (SDF-1/CXCR4) axis is involved in delivering signals related to chemotaxis, cell survival and/or proliferation, and thereby plays an important role in EMT and tumor invasiveness." (PMID 27314328, 2016).
tumor (continued). "Intranodal lymphatic sinuses are also greatly influenced by CCR7-CCL19/CCL21, CXCL12/CXCR4, S1P, IL-7, IFN-γ, integrin α4β1, and TGF-β in tumor microenvironment." (PMID 28036019, 2016). "Recent data suggest a chief position of the CXCR4/CXCL12 axis initializing androgen dependent proliferation, tumor cell motility, and metastatic growth in PCa." (PMID 27462860, 2016). "CXCL12 contributes to tumor immune escape, by inducing the migration of CXCR4+ regulatory cells, including MDSCs and Tregs toward CXCL12-rich tumor microenvironment." (PMID 27590504, 2016). "Endogenous type I IFNs inhibit CXCR4 expression on neutrophils and block CXCL12 expression in tumors leading to suppressed migration of neutrophils toward the tumor." (PMID 28066438, 2016). "Another CB2 receptor agonist, JWH-105, was found to inhibit tumor growth in a NT2.5-orthotopic mouse model and the MMTV-PyMT model and this observation corresponded to decreased pro-metastatic phospho-CXCR4 and phospho-ERK levels in vivo and in vitro." (PMID 27774065, 2016). "Blockade of FasL and CXCR4 concurrently inhibited B cell-mediated direct killing of tumor cells in an additive manner, indicating that both Fas/FasL and CXCL12/CXCR4 pathways are involved in the direct killing of 4T1 cells by 4T1 TDLN B cells." (PMID 27528023, 2016). "AMD3100, a small molecule antagonist of CXCR4, has been reported to inhibit CXCL12-induced tumor metastasis." (PMID 27191997, 2016). "Here, we showed that actein treatment suppressed the mRNA expressions of VEGFR1, CXCR4 and AKT1 in tumor tissues." (PMID 27731376, 2016). "CXCR4 signaling, a member of GPCR family, is also extensively involved in tumor progression, angiogenesis, metastasis, and survival." (PMID 26924343, 2016). "Previously, we showed that activation of the CXCL12/CXCR4 axis transactivates HER2 and promotes intraosseous tumor growth." (PMID 27809841, 2016). "The therapeutic potential of CXCR4-mAb was evaluated in immunodeficient mice harboring H1155 and A549 NSCLC tumor xenografts." (PMID 26848769, 2016). "CXCL12/CXCR4 transactivates members of growth factor receptor in PC cells, and expression of HER2 in PC patients correlates with tumor cell proliferation and activates androgen receptor signaling in advanced disease." (PMID 27809841, 2016). "Also, the chemokine receptor −4 (CXCR4) reactivity was also noticed in tumor cells with membranous, cytoplasmic and even nuclear pattern Moreover, the podoplanin tumor cell reactivity, with a membranous pattern, was more obvious at the advancing edge, at the periphery of tumor proliferations." (PMID 27871286, 2016). "However, it has been shown that CXCL12/CXCR4 might be expressed also in many tumor cells." (PMID 27041792, 2016). "Gradients of CXCL12-γ prompt greater migration of CXCR4+ cells than CXCL12-α in both the microfluidic source-sink device and the pseudo-tumor simulations and can in part be explained by high affinity for both the migration surface and receptor." (PMID 25909600, 2015). "The present study demonstrated that Nef-M1 targets CXCR4, inhibits EMT, and inhibits tumor progression." (PMID 26318034, 2015). "In contrast, the ELR− CXCL12/SDF-1 chemokine has shown to promote cell migration and proliferation acting synergistically with VEGF via CXCR4 and/or CXCR7 receptors expressed in endothelial cells within the tumor microenvironment." (PMID 26062132, 2015). "The CXC chemokine receptor-4 (CXCR4), a Gi protein-coupled receptor for the ligand CXCL12/stromal cell-derived factor-1α (SDF-1α), is expressed in various types of tumor." (PMID 25503960, 2015). "When 10,000 cells were subcutaneously inoculated in nude mice the number of implants developing tumor was 1/8 for CD133−CXCR4−, 2/8 for CD133+CXCR4−, 6/8 and 8/8 in cells respectively CD133−CXCR4+ and CD133+CXCR4+." (PMID 26020117, 2015).
tumor (continued). "During tumor development, the stromal cell-derived factor 1 (SDF-1)/CXC chemokine receptor type 4 (CXCR4) axis has been shown to be involved in the metastasis of various types of human cancer." (PMID 25846512, 2015). "Recent evidence shows that the SDF-1/CXCR4 axis and the PI3K/AKT axis functionally interact and play a significant role in tumor growth, metastasis and therapy resistance." (PMID 25775124, 2015). "First, CXCR4 is essential for metastatic spread to organs where CXCL12 is expressed and thereby allows tumour cells to access cellular niches that favour tumour cell survival and growth." (PMID 25598217, 2015). "When 1,000 cells were inoculated 0/8 for CD133−CXCR4− formed tumor, 1/8 for CD133+CXCR4−, and 5/8 and 8/8 in cells respectively CD133−CXCR4+ and CD133+CXCR4+." (PMID 26020117, 2015). "Under hypoxic conditions within the tumor mass, hypoxia-inducible factor-1a (HIF-1a) becomes up-regulated, which in turn induces high expression of CXCR4 on tumor cells." (PMID 26091099, 2015). "CXCR4 mediates cascades such as PI3K/AKT, JAK/STAT, and Rac/Rho, which are involved in cancer and promote tumour progression." (PMID 26998479, 2015). "Cell surface CXCR4, when bound to its ligand SDF-1, induces the directional migration of tumor cells." (PMID 25846512, 2015). "Although some studies have shown that CXCR4 is expressed in G3 NEC as well, comprehensive data are still missing for this tumor type." (PMID 26259237, 2015). "CXCR4 signaling, which increases VEGF-A promoter activity can promote angiogenesis and thus enhance tumor viability." (PMID 26318034, 2015). "Expression levels of multiple genes encoding for cytokines or cytokine receptors over-expressed in tumor cells or ascites fluid, such as CXCL1, CXCL2, CXCL3, IL8, IL6, IL6R, and CXCR4 were reduced in OV3/COX1KD cells." (PMID 25972361, 2015). "In the present study, we addressed the selective role of CXCR4 and CXCR7 receptors in the homing phase of metastatic dissemination using an intravenous model of tumor cell implantation." (PMID 25955316, 2015). "The most stringent stem cells feature is the tumor-forming assay; to this aim 1 × 103 and 1 × 104 OVCAR-5 and OVCAR-4 derived cells sorted as CD133−CXCR4−, CD133+CXCR4−, CD133−CXCR4+ and CD133+CXCR4+ were inoculated in nude mice." (PMID 26020117, 2015). "Single-cell suspension of control- or bevacizumab-treated tumour was stained with CD45, collagen type I and CXCR4 to detect fibrocyte-like cells." (PMID 26635184, 2015). "Among the genes that were relatively upregulated in the bevacizumab-resistant tumours compared with the control tumours, we focused on CXCL12, the ligand of CXCR4." (PMID 26635184, 2015). "Considering the inverse correlation between CXCR4 and miR-622 in the HCC tumours, we further evaluated their combined influence on patient outcome." (PMID 26404566, 2015). "In contrast to moderate tumor volume changes, we observed a robust reduction in proportion of LGR5+ (3-fold) as well as CXCR4+ cells in OSI-906 treated xenografts compared to vehicle treated controls." (PMID 25895029, 2015). "Immunohistological examination of the expression level of CXCR4 in the PDX and cell line-derived tumor models was performed using fluorescent microscopy." (PMID 26083776, 2015). "Targeting MDSC expression of CCR2 led to the downregulation of other chemokine receptors in MDSC, such as CCR1, CCR5 and CXCR4, supporting the pivotal role of CCR2-CCL2 signaling in in vivo MDSC migration and tumor growth." (PMID 26462153, 2015). "The IRS scores of the SSTR2A and 3 demonstrated an inverse significant interconnection with the grading of the neoplasms, whereas the IRS of the SSTR5 and of the CXCR4 presented a significant positive relation with the grading." (PMID 26259237, 2015). "We examined tumor metastasis promoting factors (such as MMP-9, CXCR4, NF-κB) and performed western blotting analysis after 1, 7, 14, 21 and 28 days." (PMID 25884903, 2015).